FUT2 (fucosyltransferase 2 (H blood group))
Diseases named in the same sentence as FUT2 in open-access papers (continued):
Sharing a sentence is not in itself a finding about the gene and the disease.
infection (68 papers, 2009 to 2025). The state of being infected such as from the introduction of a foreign agent such as serum, vaccine, antigenic substance or organism. "In particular, patients with a nonsense mutation in the Fut-2 gene are resistant to infection, while the overexpression of Fut-2 in human intestinal enteroids improves viral attachment and replication." (PMID 35404121, 2022). "As such, homozygous nonsense mutation (428G>A) in the FUT2 gene provides resistance to symptomatic NoV (GGII) infections." (PMID 35923409, 2022). "Second, susceptibility of HIOs to human norovirus mimics the findings of epidemiological and human infection studies where susceptibility to infection is associated with secretor status determined by fucosyltransferase 2 gene (FUT2) expression." (PMID 34071878, 2021). "In particular, the expression of FUT2 was higher in infected GES-1 cells with a higher fold change in BC2LCN lectin specific to α1-2 linked Fuc after 4 h of infection." (PMID 33557187, 2021). "Overall, the FUT2 c.461G>A variant was associated with transcriptional changes in processes related to response to infection and with increased load of potential otopathogens in the ME and decreased commensals in the NP." (PMID 35096646, 2021). "Genetic variation in FUT2 is also linked to susceptibility to infections with bacterial and viral pathogens including Helicobacter pylori, norovirus, Enterotoxigenic E. coli, and progression of HIV." (PMID 31329635, 2019). "The PTV rs601338 in FUT2 determines secretor status for ABH blood groups that has been associated with susceptibility to infection and several diseases." (PMID 29691392, 2018). "Children with the G428A homozygous mutation for inactivation of the FUT2 enzyme (se428se428) were at a significantly lower risk (48/190) of infection with norovirus (p = 0.01)." (PMID 27284939, 2016). "It should be pointed out though that we only investigated a marker for FUT2 activity, and that susceptibility for other infections might rather depend on FUT3 which determines the expression of the Lewis antigen on intestinal mucosa." (PMID 40431244, 2025). "Taken together, these results indicate that caspase-1 and −11 are involved in the infection-induced upregulation of IL-22 in the gut, consequently inducing the expression of antimicrobial C-type lectins as well as Fut2, which encodes for an enzyme important for fucosylation in the gut." (PMID 39428744, 2024). "In addition, accumulating studies have shown that dysregulation of fucosyltransferase 2 (FUT2) was associated with various human disorders, such as infection and chronic inflammatory diseases (Goto, Uematsu, and Kiyono, 2016)." (PMID 36120347, 2022). "Due to the variable HBGA polymorphism among populations, we aimed to evaluate the association between HBGA phenotypes (ABH, Lewis and secretor status) and susceptibility to rotavirus and norovirus symptomatic infection, and the polymorphisms of FUT2 and FUT3, of children from southeastern Brazil." (PMID 32992989, 2020). "Finally, susceptibility to infections with norovirus has been shown to be affected by the FUT2 genotype." (PMID 30405986, 2018). "To obtain HIOs with right HBGA phenotypes as a prerequisite for huNoV interaction and infection, we first screened several available stem cell lines for a functional and a mutant FUT2 gene encoding the FUT2, the key enzyme that catalyzes the production of H antigen to initiate the secretor pathway." (PMID 28974702, 2017). "Moreover, genotyping for the FUT2 SNP showed that children with the G428A homozygous mutation for inactivation of the FUT2 enzyme (se428se428) are significantly at a lower risk of infection with norovirus." (PMID 27284939, 2016).
infection (continued). "Loss of functional FUT2 activity was associated with better resistance to some pathogens such as specific Norovirus genotypes and Helicobacter pylori, with the trade-off to have a higher risk for infections by other pathogens affecting respiratory, urinary tract or the gastro-intestinal systems." (PMID 28182762, 2017). "The P genotype of rotavirus was detected in 2.3% (3/132) of FUT2− compared with 8.8% (47/536) of FUT2+ children (p = 0.009), supporting that at least infection by this subtype is restricted by secretor status." (PMID 40431244, 2025). "The Fut2 gene has been reported to play a key role in the response against infection-related injury, gastric acid secretion, and gastrointestinal motility." (PMID 39767078, 2024). "Moreover, a FUT2 polymorphism was associated with the human faecal microbiota composition and diversity, which could explain host-microbe interactions and susceptibility to infection." (PMID 35976909, 2022). "At 4 h post-infection, the expression level of FUT2 was higher in GES-1 cells infected with H. pylori strain M84, P164, YN4-62, and the expression level of FUT4 was higher in GES-1 cells infected with H. pylori strain HLJ030 and YN4-62." (PMID 33557187, 2021). "These pathogen-specific associations also appear modest in comparison to intra-subject-level exposures, such as rotavirus vaccine status—50% protective against severe rotavirus morbidity —and maternal FUT2 secretor status—a 37% reduction in LT-ETEC infection." (PMID 33147841, 2020). "J4Fut2−/−/FUT2 was permissive to infection by all four viruses, based upon increases in viral genome equivalents (GEs) at 24 hpi." (PMID 32184242, 2020). "One day post infection (p.i.), the cecal tissue of Fut2-/- mice contained more S. Typhimurium than Fut2+/+ mice in agreement with the observations of Goto and colleagues." (PMID 31329635, 2019). "These concordant data provide strong evidence that FUT2 (secretor) and FUT3 (Lewis) genetic polymorphisms contribute to susceptibility to major strains of RVs and therefore that HBGAs are involved in the infection process." (PMID 30154494, 2018). "The increased levels of fucose in the tissue during infection are consistent with the observed increase in transcription levels of FUT2 and FUT4, coding for enzymes transfering Fuc α-1,2 and Fuc α-1,3 respectively, on mucins." (PMID 21569362, 2011). "Thus, a functional FUT2 gene (secretor phenotype), which expresses the HBGAs acting as an entry factor for HuNoV, is a feature to consider when selecting or optimizing NoV infection experiments." (PMID 41218799, 2025). "In summary, the HLA, MUC2 and FUT2 loci show strong candidacy for a role in sputum production, with overlap with infection and related phenotypes and known mechanistic interactions between the genes at the FUT2 and MUC2 loci, suggesting that these signals are likely to be robust." (PMID 37263751, 2023). "In conclusion, we investigated the changes in fucosylated glycans and FUTs in GES-1 cells infected with H. pylori strains from different sources, and our data demonstrate for the first time that the higher levels of expression of FUT1 and FUT2 were detected within 2 h post-infection." (PMID 33557187, 2021). "The higher expression of FUT1 and FUT2 was detected within 2 h post-infection." (PMID 33557187, 2021). "IL-22 can also induce the expression of fucosyltransferase 2 (Fut2) to improve the glycosylation of the proteins expressed on the surface of enterocytes, which can facilitate to protect against infection by intestinal pathogens (e.g., Salmonella enterica serotype typhimurium)." (PMID 34885715, 2021). "Overexpression of the FUT2 gene increased virus binding to the cells but did not make them susceptible to infection." (PMID 32184242, 2020).
infection (continued). "Individual differences in susceptibility to infections by different genotypes have been described depending on the expression of histoblood group antigens (HBGA), the expression of which is primarily determined by the FUT2 gene." (PMID 33266188, 2020). "Therefore, this study aimed to analyze the association between rotavirus and norovirus symptomatic infection and HBGA phenotypes, in addition to FUT2 and FUT3 genes polymorphisms, in children from Southeastern Brazil." (PMID 32992989, 2020). "Mice lacking Fut2 are more susceptible to S. Typhimurium infection at an early time point post infection, as demonstrated by Goto and colleagues and confirmed in the present study." (PMID 31329635, 2019). "Also characteristic for SFB was the induction of fructosyltransferase 2 (Fut2) which was shown to foster bacterial species that metabolize fucosylated substrates and protect against infection with Salmonella typhimurium." (PMID 31229354, 2019). "In addition, lipocalin-2 concentrations were similar in colons of both Fut2+/+ and Fut2-/- mice after infection with S. Typhimurium ΔaroA ΔstdA." (PMID 31329635, 2019). "HBGA expression on the intestinal epithelia they may serve as host receptors to which enteric viruses and bacteria attach to establish infection, and individuals expressing at least 1 functional copy of the FUT2 gene are called secretors." (PMID 30768135, 2019). "The early bifidobacteria establishment and possibly also the breast milk FUT2 dependent oligosaccharides per se might lead to enhanced infant immune development and protection from infection." (PMID 28182762, 2017). "However, in a recent study, significantly increased infectivity of P RVs was observed in CHO cells following transfection with the FUT2 gene, which led to a conclusion that the α 1,2-fucose played a major role in P binding and infection." (PMID 24244290, 2013). "Moreover, a French study suggested that RV P infections were completely absent in individuals with the non-secretor phenotype, namely, the homozygous nonsense mutation FUT2." (PMID 35923409, 2022). "However, whether FUT2 expression alone is critical for infection remains unproven, since routinely used secretor-positive transformed cell lines are resistant to HuNoV replication." (PMID 32184242, 2020). "In addition, the association between the secretor status and infection, initially demonstrated for noroviruses, has also been shown by recent studies for rotavirus, which has demonstrated a correlation between infection and the presence of a functional FUT2 phenotype." (PMID 32992989, 2020). "In this retrospective study, we investigate if a FUT2 genetic polymorphism is associated with the phenotypic non-secretor status found in Bangladesh and if this mutation may be related to increased susceptibility to symptomatic ETEC CFA/I infection." (PMID 28878367, 2017). "Individuals homozygous for nonfunctional FUT2 alleles are classified as non-secretors and are highly resistant to symptomatic NoV infection, as the absence of functional glycans limits viral binding to intestinal receptors, thereby preventing cell entry and infection." (PMID 41156706, 2025). "Anti-ABO antibodies could also help controlling infection by other coronaviruses as these viruses are highly glycosylated and replicate in epithelial cells of the upper respiratory tract that strongly express ABH antigens in accordance with the ABO and FUT2 genes polymorphisms." (PMID 33499228, 2021). "With the addition of FUT2, J4 expressed Leb instead of Lea, indicative of functional FUT2 and FUT3 activities, and the line became permissive to GI.1, GII.3, GII.4, and GII.17 infection." (PMID 34696500, 2021). "We compared infection and diarrhea from these pathogens between FUT2+/FUT3− and FUT2+/FUT3+ children." (PMID 30768135, 2019).
infection (continued). "The relationships of DARC to P. vivax, FUT2 to norovirus, CCR5 to HIV-1, and SAO to P. falciparum constitute defective receptor or entry points which thus are protective against infection." (PMID 30405986, 2018). "Non-secretor individuals, who lack the functional FUT2 gene and therefore do not express HBGAs on intestinal tissues, are generally resistant to infection by prevalent genotypes such as GI.1 and GII.4." (PMID 41218799, 2025). "While Fut2 transcription was significantly increased (~10-fold) in the ceca of infected WT mice compared to baseline, it was not induced upon infection of Casp1/11−/− mice." (PMID 39428744, 2024). "Fucosylation of IECs is carried out by fucosyltransferase 2 (FUT2), and when this enzyme is deleted or inactivated, infection and subsequent replication of GII.4 norovirus is not observed." (PMID 37766335, 2023). "As in North America and the rest of Europe, most of the Spanish population has a Lewis-positive secretor phenotype (FUT2+), which has been related to infection by genotypes P and P, but not by genotype P." (PMID 30974776, 2019). "Genotyping of 34 symptomatic individuals regarding the FUT2 gene revealed that one patient was, surprisingly, a non-secretor, hence indicating secretor-independent infection." (PMID 19440360, 2009). "Additionally, Fut2 expression transiently increased in the mouse ME after infection with non-typeable Haemophilus influenzae (NTHi), which is a common otopathogen in humans." (PMID 35096646, 2021). "Several studies have demonstrated that secretor status is associated with susceptibility to human norovirus (HuNoV) infection; however, previous reports found that FUT2 expression is not sufficient to allow infection with HuNoV in a variety of continuous laboratory cell lines." (PMID 32184242, 2020). "Approximately 20% of Caucasians do not express gastrointestinal HBGAs due to the lack of a functional fucosyltransferase 2 (FUT2) gene (“nonsecretors”), and consequently these individuals have a significantly reduced susceptibility to infection with noroviruses." (PMID 25832298, 2015). "Even though HBGA association is essential for in vivo Norwalk infection, it is not sufficient to overcome the block to in vitro virus propagation – cell lines expressing HBGAs are resistant to infection and transfection of FUT2 into cells does not facilitate infection." (PMID 21994656, 2010). "Given the evidence of enhanced gene abundance in response to dietary 2′FL, further experiments could be powered to detect 2′FL protection against infection and provide direct evidence of augmented catabolism of luminal 2′FL, particularly among infants negative for FUT2." (PMID 36211486, 2022). "Lack of intestinal microbiota generally results in downregulation of FUT2, and it is not known how diminished FUT2 levels could affect RVwa infection in mice, especially given that another entry mediator of P RV, the Lewis b antigen, is not produced in this host." (PMID 34356911, 2021). "However, these initial correlative studies did not address whether FUT2 expression alone is critical for infection." (PMID 34071878, 2021). "Non-secretors are protected from infection by strains from GII.4 and possibly also GII.3 strains, while other less common strains such as GII.2 seem to infect in a FUT2-independent manner." (PMID 40431244, 2025). "Taken together, these results show that functional FUT2 is sufficient and critical for replication of multiple HuNoV strains and that GII.3 is capable of infection in some secretor-negative HIE lines." (PMID 32184242, 2020).
cancer (28 papers, 2012 to 2026). A tumor composed of atypical neoplastic, often pleomorphic cells that invade other tissues. "The regulation of genes encoding key glycosyltransferases that allow a switch from the a-series to the b-series gangliosides, as well as FUT1 and FUT2 regulation, is a major element to understand the specific cancer-associated ganglioside expression." (PMID 34200284, 2021). "Given the strong connection between dysfunctional ISCs and cancer development, whether Fut2 deficiency in ISCs contributes to the pathogenesis of CRC during aging may be a meaningful question in future studies." (PMID 38550777, 2024). "Isolating the underlying mechanisms for BKV response is challenging because FUT2 is a pleiotropic locus associated with diverse phenotypes, including autoimmune and inflammatory conditions, serum lipids, B vitamins, alcohol consumption, and even certain cancers." (PMID 33109261, 2020). "In particular, variations in both FUT2 and FUT3 have been associated with various types of disease including different types of cancer and intestinal diseases." (PMID 40244459, 2025). "Recently, FUT2 has been shown to be involved in cancer progression, including cancer cell proliferation, invasion, metastasis, and cell signaling." (PMID 36552800, 2022). "FUT2 was significantly upregulated in seven cancer types but downregulated in six cancer types compared with normal tissues." (PMID 36552800, 2022). "The production of these glycans is increased in various cancers, hence to design and develop specific inhibitors of FUT2 is a therapeutic strategy." (PMID 34648519, 2021). "To date, FUT1 and its glycan products are relatively better studied than FUT2 in relation to cancers." (PMID 30854233, 2019). "These are consistent with the effect of knockdown of FUT2 on cancer invasion and migration in A549 cells." (PMID 29228607, 2017). "In our database, FUT2 exemplifies this complexity, containing several distinct haplotypes formed by diverse combinations of cancer GWAS, non-cancer GWAS, and other coding variants." (PMID 41261743, 2026). "Increased FUT2 and FUT8 expression has been linked to cancer." (PMID 38456503, 2024). "Recent reports have revealed important functions of FUT2 in cancers." (PMID 36973740, 2023). "Fucosyltransferase 2(FUT2) and its induced α-1,2 fucosylation is associated with cancer metastasis." (PMID 36973740, 2023). "In contrast, Secretors are at higher risk of infections associated to other pathogens that require glycosylated receptors related to FUT2 activity, mainly Norovirus, Rotavirus, Coronavirus, HIV...) and susceptibility to some types of cancers and chronic diseases." (PMID 35079053, 2022). "Alpha1,2-fucosyltransferases, FUT1 and FUT2, which transfer fucoses onto the terminal galactose of N-acetyl-lactosamine via α1,2-linkage have been shown to be highly expressed in various types of cancers." (PMID 27560716, 2016). "The different roles of Fut2 in cancers may be due to differences in the tissues and organs." (PMID 36739428, 2023). "We found that FUT2, FUT3, and FUT8 exhibited significantly elevated expression levels in older patients with both cancers when compared with young patients." (PMID 38456503, 2024). "Therefore, the role of Fut2 in cancer development may be tissue specific." (PMID 36739428, 2023). "In light of the impact of FUT1 and FUT2 on cancer stem cells (CSC) and cell metastasis, we investigated the role of FUT1 and FUT2 in epithelial-mesenchymal transition (EMT), which was considered a hallmark of CSC and metastasis." (PMID 30854233, 2019). "In poorly differentiated malignant tumors, theywere mostly absent.Conclusion: Considering these results we suggest the use of this method to monitor probable preneoplastic lesionsin risk population, especially in those with no secretor status (absence of FUT2 gene)." (PMID 22157667, 2012). "Further IHC assay showed that FUT2 is increased in cancer tissue, but do not correlate with clinical stage." (PMID 29228607, 2017).